TMEM218 (transmembrane protein 218)
Description:
May be involved in ciliary biogenesis or function.
Synonyms: JBTS39
Tractability: Antibody: UniProt predicts a signal peptide or a membrane-spanning region; the Human Protein Atlas places it where antibodies can reach.
Gene: Protein-coding gene on chromosome 11 (125,094,386 to 125,111,870, reverse strand). Ensembl gene ENSG00000150433.
Subcellular location: Membrane; Cell projection, cilium
Subcellular location (Human Protein Atlas): Plasma membrane; Cytosol
Gene Ontology:
Molecular function: protein binding
Cellular component: cilium; membrane
Genetic constraint (gnomAD): Loss-of-function variants: 4 observed, 7.52 expected, observed/expected ratio (o/e) 0.53, 90% interval 0.26 to 1.21. That is too few expected variants to judge how well the gene tolerates losing a copy. Missense variants: 68 observed, 98.27 expected, observed/expected ratio (o/e) 0.69, 90% interval 0.57 to 0.85. Synonymous variants: 37 observed, 41.23 expected, observed/expected ratio (o/e) 0.9, 90% interval 0.69 to 1.18.
Homologues: Orthologues: chimpanzee TMEM218 (100% identical), macaque TMEM218 (97% identical), dog TMEM218 (86% identical), rabbit TMEM218 (85% identical), mouse Tmem218 (81% identical), pig TMEM218 (80% identical), guinea pig TMEM218 (79% identical), rat Tmem218 (55% identical), zebrafish tmem218 (54% identical).
Diseases named in the same sentence as TMEM218 in open-access papers:
TMEM218 is named in the same sentence as 4 diseases in open-access papers, as found by Europe PMC text mining. Sharing a sentence is not in itself a finding about the gene and the disease. The quoted sentences say what the papers report.
ciliopathy (1 paper, 2016). A genetic disorder of the cellular cilia or the cilia anchoring structures, the basal bodies, or of ciliary function. "Aside from Tmem218 and Tmem80, one of the few TZ proteins that remains to be linked to one or more ciliopathies is Tmem17." (PMID 26982032, 2016). "It will be interesting to confirm and further investigate in mammalian cells our overall model for TZ assembly as well as obtain evidence for the involvement of the novel TZ proteins we uncovered (Tmem218 and Tmem80) in ciliopathies." (PMID 26982032, 2016). "While the murine protein was not characterised, we show that the nematode orthologue (TMEM-218) localises to the TZ, as with other ciliopathy-associated TZ proteins." (PMID 26982032, 2016). "Furthermore, TMEM-218 can be positioned genetically and hierarchically within the MKS module, likely as a peripheral component, similar to MKS-3 (Tmem67), JBTS-14 (Tmem237), and MKS-6 (Cc2d2a), which are all ciliopathy-associated." (PMID 26982032, 2016).
obstructive sleep apnea (1 paper, 2022). "Interestingly, TMEM218 was identified as a common gene between obstructive sleep apnea and AD." (PMID 35883662, 2022).
retinal degeneration (1 paper, 2016). Degeneration of the retina. "Recently, disruption of Tmem218 in a mouse mutagenesis screen was found to cause retinal degeneration and NPHP phenotypes that resemble SLNS." (PMID 26982032, 2016).
TMEM218 also shares sentences with these, for which no sentence is quoted: cancer (1 paper).